BST2 (bone marrow stromal cell antigen 2)
Diseases named in the same sentence as BST2 in open-access papers (continued):
Sharing a sentence is not in itself a finding about the gene and the disease.
breast cancer (continued). "The effect of BST-2 on cell invasion is evident in the response of the aggressive human breast cancer cell line (MDA-MB-231) and four isogenic murine cancer cell lines." (PMID 29299143, 2017). "Mice injected with metastatic breast cancer cell lines in which BST‐2 was downregulated showed decreased tumor growth at the primary and metastatic sites with resultant increase in survival of tumor bearing mice." (PMID 27042298, 2016). "Treatment of low grade (grades 1 and 2) breast cancer cell lines with TGF‐β resulted in suppression of BST‐2 transcripts." (PMID 27042298, 2016). "In cancer cells, BST‐2 expression is transcriptionally regulated in TGF‐β responsive breast cancer cells." (PMID 27042298, 2016). "Nonetheless, soluble factors released by mammary tumor cells suppress IFNα and IFNγ but induce BST‐2 expression." (PMID 27042298, 2016). "al., showed that elevated BST‐2 expression renders high grade breast cancer cells resistant to pro‐apoptotic drug (tamoxifen and staurosporine) treatment." (PMID 27042298, 2016). "The ubiquitous presence of BST‐2 in breast cancer cells and the enhanced cell adhesion of these cells suggest effect on tumor growth." (PMID 27042298, 2016). "Bone marrow stromal antigen 2 (BST-2) is a known anti-viral gene that has been recently identified to be overexpressed in many cancers, including breast cancer." (PMID 25860442, 2015). "In this study, we conducted meta-analysis of the methylation status of the BST-2 gene because BST-2 has been associated with development and progression of breast cancer in vivo." (PMID 25860442, 2015). "Although BST-2 expression in HER2 and basal tumor subtypes is not statistically different from normal tissues, it is well stablished that BST-2 is overexpressed in the most aggressive forms of breast cancer." (PMID 25860442, 2015). "We conclude that a greater frequency of BST-2 hypomethylation was observed in breast cancer tissues and cells compared to normal breast tissues and cells." (PMID 25860442, 2015). "Evaluation of BST-2 expression in different breast cancer subtypes show that while all cancer subtypes have elevated BST-2, tumors categorized as luminal B subtype has the highest BST-2 level compared to normal mammary tissue." (PMID 25860442, 2015). "Overall, these data show that BST-2 DNA is hypomethylated in mammary tumors compared to normal mammary tissue." (PMID 25860442, 2015). "Recent studies have demonstrated that the mRNA and protein expression of BST-2 are elevated in various cancers including: head and neck cancer, oral cavity cancer, glioblastoma, lung cancer, endometrial cancer, lymphomas, and breast cancers." (PMID 25860442, 2015). "In breast cancer, BST-2 expression is highest in metastatic tumors compared to primary tumors, and normal mammary gland tissues have the lowest expression." (PMID 25860442, 2015). "Since demethylation of CpG sites strongly associates with increased expression of BST-2 in tumor tissues, we next analyzed the methylation level of BST-2 in different breast cancer subtypes." (PMID 25860442, 2015). "To evaluate the level of BST-2 expression in different metastatic cells, we utilized breast cancer cell lines that originated from various metastatic sites." (PMID 25860442, 2015). "For this purpose, we used GEO datasets GSE28976 and GSE36683 (for MCF-7s only) to analyze the effect of DAC on BST-2 methylation in several human breast cancer cell lines." (PMID 25860442, 2015). "On the basis of this finding, we assessed correlation in patterns of BST-2 mRNA expression and BST-2 methylation in well-established breast cancer cell lines downloaded from GEO dataset GSE10797." (PMID 25860442, 2015). "BST-2 expression levels and BST-2 DNA methylation status at specific CpG sites on the BST-2 gene were compared for various breast tumor molecular subtypes and breast cancer cell lines." (PMID 25860442, 2015).
breast cancer (continued). "BST-2 is critical for the invasiveness of breast cancer cells and the formation of metastasis in vivo." (PMID 25860442, 2015). "In this study, we demonstrated that BST-2 expressed in cancer cells promoted breast cancer development and progression by altering the behavior of cancer cells." (PMID 25499888, 2014). "BST-2 in breast tumors and mammary cancer cells is a strong predictor of tumor size, tumor aggressiveness, and host survival." (PMID 25499888, 2014). "Meta-analysis of large-scale human breast cancer data from the GEO and TCGA was used to assess the level of BST-2 mRNA in breast tumors." (PMID 25499888, 2014). "To establish a system to analyze the functional implication of BST-2 expressed in cancer cells, we suppressed BST-2 expression in two murine mammary cancer epithelial cell lines, E0771 cells and 4T1 cells." (PMID 25499888, 2014). "We studied BST-2 expression in different human breast cancer cells compared to normal mammary epithelial cells." (PMID 25499888, 2014). "As expected, BST-2 expression was higher in the most aggressive form of breast cancer, IDC, compared to DCIS." (PMID 25499888, 2014). "Large breast tumors have higher BST-2 expression compared to smaller tumors as revealed by meta-analysis of human breast cancer data using the GEO dataset GSE4922." (PMID 25499888, 2014). "To determine the effect of BST-2 in primary mammary tumor development, we inoculated BST-2-expressing shControl and BST-2-suppressed sh413 4T1 cells into the mammary fat pads of BALB/c mice and evaluated tumor growth." (PMID 25499888, 2014). "Meta-analysis of tumors from breast cancer patients obtained from the Gene Expression Omnibus (GEO) and The Cancer Genome Atlas (TCGA) datasets were evaluated for levels of BST-2 expression and for tumor aggressiveness." (PMID 25499888, 2014). "Baseline TGFβ levels (approximately 1 ng/ml in 2% serum supplemented growth media used here) sufficed to induce AP2 binding to the BST2 promoter in 3/3 TGFβ responsive low/intermediate grade breast cancer cell lines." (PMID 23840623, 2013). "Consistent with its localization in other cell types in various human tissues, BST2 immunostaining of unfixed live breast cancer cells displayed significant accumulation at the cell surface." (PMID 23840623, 2013). "This suggests the possibility of resveratrol induced BST2 promoter repression by AP2 in TGFβ-resistant cells analogous to that occurring normally in TGFβ-responsive breast cancer cells." (PMID 23840623, 2013). "Antibody based targeting of BST2 upregulation in B cell lymphoma lesions delayed tumor growth supporting our observations of a BST2-mediated role in breast cancer outcome." (PMID 23840623, 2013). "In a subset of breast cancer patients treated with pro apoptotic hormonal therapy, BST2 expression correlated with a trend for poor clinical outcome, further supporting its role in conferring an anti apoptotic phenotype." (PMID 23840623, 2013). "Genomic profiling of an expanded panel of breast cancer cell lines revealed BST2 among the top 100 significant genes differentially expressed in high vs. low grade tumor derived cell cultures - all in the proliferative state." (PMID 23840623, 2013). "We have defined an oncogenic framework for BST2 in breast cancer by correlative and functional analysis of clinical tissue and novel in vitro model systems, respectively." (PMID 23840623, 2013). "Overall, BST2 is a strong candidate for consideration as a theranostic in the target discovery pipeline for breast cancer." (PMID 23840623, 2013). "We show that the transcription factor, AP2 is a critical component of TGFβ-mediated regulation of BST2 in breast cancer." (PMID 23840623, 2013). "Here, we have established functional phenotypes resulting from differential BST2 expression by using breast cancer cell lines of varying grade." (PMID 23840623, 2013).
breast cancer (continued). "In our present study, we employed RNAi techniques to suppress the BST2 expression to investigate the effects of BST2 modulation on breast cancer cell proliferation, migration and invasion." (PMID 19338666, 2009). "We conclude that we have demonstrated that the BST2 expression is significantly increased in bone metastatic breast cancer." (PMID 19338666, 2009). "We have recently made the novel observation of the BST2 protein expression in human breast cancer cell lines." (PMID 19338666, 2009). "In order to discover a novel, simple and sensitive biomarker in bone metastatic breast cancer, we also measured serum BST2 level using ELISA." (PMID 19338666, 2009). "cDNA microarray analysis was used to compare the BST2 gene expression between a metastatic to bone human breast cancer cell line (MDA-231BO) and a primary human breast cancer cell line (MDA-231)." (PMID 19338666, 2009). "Most importantly, the breast cancer cell line that transfected with BST2 demonstrated increased BST2 expressions, which was associated with increased cancer cell migration and cell proliferation." (PMID 19338666, 2009). "Our results indicated that the BST2 expression was significantly increased in the bone metastatic breast cancer tissues." (PMID 19338666, 2009). "Thirty-six (84%) of 43 breast cancer patients with bone metastasis had significantly increased serum levels of BST2 as indicated by ELISA." (PMID 19338666, 2009). "The migration ability of BST2 on breast cancer cells was analyzed using an in-vitro migration assay." (PMID 19338666, 2009). "The purpose of our present study is to investigate the expression and the role of BST2 in bone metastatic breast cancer." (PMID 19338666, 2009). "The microarray demonstrated over expression of the BST2 gene in the bone metastatic breast cancer cell line (MDA-231BO) compared to the primary human breast cancer cell line (MDA-231)." (PMID 19338666, 2009). "We found BST2, an important bone marrow stromal protein, to be significantly up-regulated in the bone metastatic breast cancer cell line, MDA-231BO, compared to MDA-231 (Expression ratios = 3.2, 4.5, 4.29, 3.97 and 4.9)." (PMID 19338666, 2009). "BST2 is reported to be highly expressed in various tumors and is involved in the proliferative potential of cancers such as esophageal, gastric, colorectal, and breast cancer." (PMID 37389178, 2023). "However, chronic infection with Mouse mammary tumor virus has also been shown to suppress both IFNα and IFN-γ, while BST2 remains elevated in breast cancer." (PMID 35865015, 2022). "Findings from many labs have shown that BST-2 is overexpressed in several cancers including lung cancer, head and neck carcinomas, oral cavity cancers, glioblastomas, endometrial cancer, lymphomas, and breast cancer." (PMID 32155736, 2020). "Moreover, BST2 also promotes invasion and migration of tamoxifen-resistant breast cancer cells MCF-7 via TCF-7." (PMID 31957537, 2020). "The overexpression of BST2 has been associated with increased metastasis in MDA-231BO in comparison to the primary human nonmetastatic MDA-231 breast cancer cell line." (PMID 31957537, 2020). "Indeed, the levels of BST-2 is high in many breast cancer cell lines and its expression is regulated in part by DNA methylation, where BST-2 expression patterns in tumors and cancer cells correlate with hypomethylated BST-2 DNA." (PMID 32872253, 2020). "Therefore, this manuscript presents additional findings documenting targeting BST-2 as a promising strategy to treat breast cancer." (PMID 32872253, 2020). "Moreover, examination of TCGA dataset disclosed a marked increase in BST2 expression in breast cancer and CBX6 and BST2 were negatively correlated in breast cancer (Spearman r = −0.1804, P < 0.0001)." (PMID 30655550, 2019). "In view of the combined results, BST2 is proposed as an ideal therapeutic target for breast cancer." (PMID 30655550, 2019).
breast cancer (continued). "On the basis of these findings, we hypothesized that a molecule that mimics the BST-2 extracellular domain will efficiently block BST-2-mediated breast cancer cell to cell interaction." (PMID 29523843, 2018). "It was within this context that we became interested in how the expression of BST-2 might be playing a role in breast cancer." (PMID 29523843, 2018). "Thus far, we have established that BST-2 is an important regulator of various breast cancer aggressive phenotypes and a regulator of metastatic processes." (PMID 30514852, 2018). "BST-2 DNA is hypomethylated in breast cancer cells leading to its overexpression." (PMID 30514852, 2018). "Exploration of the molecular and structural basis of BST-2-mediated migration and invasion could improve our understanding of the contribution of BST-2 in shaping the intricate cellular processes involved in breast cancer progression." (PMID 29299143, 2017). "In summary, we have demonstrated how BST-2 activity shapes the function of breast cancer cells." (PMID 28300825, 2017). "Importantly, BST-2 dimerization promotes tumor growth in preclinical breast cancer models in vitro and in vivo." (PMID 28300825, 2017). "Given that BST-2 in breast cancer cells mediates cancer cell adhesion and anchorage-independent growth, we hypothesized that BST-2 functions to promote tumor cell survival through inhibition of anoikis." (PMID 28300825, 2017). "Thus, in some cancers, constitutive upregulation of BST‐2 expression and BST‐2 activity correlates with disease pathology in human and have been functionally demonstrated to cause disease in mouse models of breast cancer." (PMID 27042298, 2016). "In vitro, overexpression of BST‐2 in breast cancer cells enhanced cell migration, invasion, proliferation, and anchorage‐independent growth 119, 123, 129 whereas BST‐2 suppression results in reduced migration, invasion, anchorage‐independent growth but not cell proliferation." (PMID 27042298, 2016). "BST2 is an antiviral gene that is overexpressed in many cancers, including breast cancer." (PMID 27359105, 2016). "In this case, the outcome of elevated BST‐2 in breast cancer is poor survival as revealed by meta analyses of large human datasets 123, 131 and experimental evidence in mouse models of breast cancer." (PMID 27042298, 2016). "This pattern of BST‐2 demethylation in breast cancer may be important for cancer cells to acquire an invasive potential." (PMID 27042298, 2016). "In contrast to the effects of BST‐2 on breast cancer cells, in HT1080 (human fibrosarcoma epithelial cell line) and MDCK (canine kidney cells) cells, overexpression of BST‐2 decreased cell growth and migration due to reduced matrix metalloproteinase 2 (MMP‐2) activity." (PMID 27042298, 2016). "Our study suggests that the DNA methylation pattern and expression of BST-2 may play a role in disease pathogenesis and could serve as a biomarker for the diagnosis of breast cancer." (PMID 25860442, 2015). "Additionally, it is of interest to determine how changes in BST-2 DNA methylation pattern relate to the molecular pathology in breast cancer initiation, progression, and metastasis." (PMID 25860442, 2015). "Furthermore, in aggressive breast cancers and cancer cell lines, such as basal and triple-negative tumors, BST-2 is hypomethylated at CpG sites downstream of the BST-2 TSS." (PMID 25860442, 2015). "Although the regulation of BST-2 in immune cells is unraveling, it is unknown how BST-2 expression is regulated in breast cancer." (PMID 25860442, 2015). "Upon BST-2 knockdown, breast cancer cells lose their capacity to grow and thrive in vivo." (PMID 25860442, 2015). "Together, these data suggest that downregulation of BST-2 expression in breast cancer cells delays mammary tumor onset and may impair the ability of primary tumors to thrive." (PMID 25499888, 2014). "BST-2 contributes to the emergence of neoplasia and malignant progression of breast cancer." (PMID 25499888, 2014).
breast cancer (continued). "However, suppressing BST-2 expression decreased the onset of primary mammary tumor growth thereby increasing tumor latency, and decreasing tumor cell metastases and growth at distal sites, as in lung colonization." (PMID 25499888, 2014). "Grade associated variation in BST2 transcript levels was first confirmed by QPCR analysis of breast cancer cell lines normalized to that of non-malignant primary breast epithelial cultures derived from reduction mammoplasty tissue." (PMID 23840623, 2013). "Closely parallel to our observations of the negative regulation of BST2 in breast cancer, AP2 is involved in the repression of promoter sequences of the oncogene, ERBB2, evident as an inverse correlation between AP2 and ERBB2 immunolocalization in archival tumor specimens." (PMID 23840623, 2013). "A trend was evident, whereby patients in the top 2 tertiles of BST2 expression showed a shorter interval of disease-free survival compared to those with lower BST2 expression in the primary tumor (p = 0.12), supporting our in vitro molecular and functional studies on breast cancer cell lines." (PMID 23840623, 2013). "Using breast cancer cell lines derived from low and intermediate histopathologic grade invasive primary tumors that maintain growth-suppressive TGFβ signaling, we demonstrate that BST2 is negatively regulated by the TGFβ axis in epithelial cells." (PMID 23840623, 2013). "Additionally, we further assessed the role of BST2 expression in the regulation of cell cycles progression and apoptosis in breast cancer cells, and we induced BST2 expressions in a breast cancer cell line, MDA-231." (PMID 19338666, 2009). "Furthermore, serum levels of BST2 measured by ELISA were also significantly higher among patients with breast cancer metastatic to bone compared to breast cancer patients without metastatic to bone (P < .0001)." (PMID 19338666, 2009). "We induced BST2 expressions in a breast cancer cell line (MDA-231)." (PMID 19338666, 2009). "As such, targeting BST-2 in tumors may be an effective therapeutic approach against breast cancer." (PMID 32872253, 2020). "We envision that in a tumor context, BST-2‐regulated heterotypic interactions between cancer cells and the tumor microenvironment may promote invadopodia formation, intravasation, extravasation, and metastasis of breast cancer cells." (PMID 30514852, 2018). "Finally, we have shown that B49/B49Mod1 that mimics and binds the extracellular domain of BST-2 could be therapeutically useful in the treatment of breast cancer." (PMID 29523843, 2018). "However, the distinct structural elements of BST-2 that mediate breast cancer cell motility remain unknown." (PMID 29299143, 2017). "Therefore, BST-2:BST-2 dimerization may transmit survival signals or suppress proapoptotic factors in breast cancer cells, creating a microenvironment that allows cells to grow independent of anchor." (PMID 28300825, 2017). "Moreover, the average methylation beta-value for probes 3 to 9 was inversely correlated to their corresponding BST-2 mRNA levels among all breast cancer cell lines analyzed, providing additional support for a link between BST-2 expression and methylation status." (PMID 25860442, 2015). "Therefore, BST-2 overexpression from DNA hypomethylation could influence breast carcinogenesis and could predict breast cancer prognosis or therapeutic response." (PMID 25860442, 2015). "Therefore, BST-2 may serve as a biomarker for aggressive breast cancers and as a potential target for the development of new therapeutics for BST-2-dependent cancers." (PMID 25499888, 2014). "We believe that BST2 may be a potential biomarker in bone metastatic breast cancer." (PMID 19338666, 2009). "However, the BST2 protein expressions aren't identified in the breast cancer." (PMID 19338666, 2009). "We believe that BST2 may be a potential biomarker in breast cancer with bone metastasis." (PMID 19338666, 2009).